BRCA1 (BRCA1 DNA repair associated)
Diseases named in the same sentence as BRCA1 in open-access papers (continued):
Sharing a sentence is not in itself a finding about the gene and the disease.
Gynecomastia (1 paper, 2020). Abnormal development of large mammary glands in males resulting in breast enlargement. "ATM, BRCA1, PALB2, RAD51B, and XRCC3 promoter methylation levels were evaluated in paired tumor, normal tissue, and adjacent lymph nodes, and in gynecomastia tissue samples." (PMID 32295201, 2020). "Among the five gene promoters tested, only two - RAD51B and XRCC3—disclosed statistically significant differences between tumor and gynecomastia tissue samples, whereas ATM, BRCA1, and PALB2 did not." (PMID 32295201, 2020).
Helicobacter pylori (1 paper, 2025). "It is possible that the increased levels of baseline DNA damage observed in BRCA1 and BRCA2 carriers acts a primer for gastric carcinogenesis, which upon addition of a second insult, such as a Helicobacter pylori (H. pylori) infection, may then more aggressively drive gastric carcinogenesis." (PMID 41256354, 2025).
hemophilia A (1 paper, 2021). The most common form of hemophilia characterized by spontaneous or prolonged hemorrhages due to factor VIII deficiency. "For example, haplotype analysis revealed three founder mutations (BRCA1 c.68_69delAG, c.5266dupC, and BRCA2 c.5946delT) in the Ashkenazi Jewish population, and a recurrent F8 mutation (c.6046C>T) causing hemophilia A in a northern Italian population." (PMID 34630384, 2021).
Hepatitis (1 paper, 2020). Inflammation of the liver.
HIV-1 infection (1 paper, 2015). The type species of lentivirus and the etiologic agent of acquired immunodeficiency syndrome (AIDS). "BRCA1 presence at the HIV-1 promoter highlights a novel function of the multifaceted protein in HIV-1 infection." (PMID 25879655, 2015).
idiopathic pulmonary fibrosis (1 paper, 2021). Idiopathic pulmonary fibrosis (IPF) is a nonneoplastic pulmonary disease that is characterized by the formation of scar tissue within the lungs in the absence of any known cause. "BRCA1 is a well-established tumor suppressor, and the down-regulation of DNA repair proteins, including BRCA1, was implicated in COPD and idiopathic pulmonary fibrosis." (PMID 34769496, 2021).
infarction (1 paper, 2020). A localised pathological necrosis of tissue resulting from obstruction of the blood supply usually by a thrombus, an embolus, or vascular torsion. "Administration of TGR5 siRNA or BRCA1 siRNA significantly abolished the protective effect of INT777 on infarction volume, neurological deficits and brain edema at 24 h after MCAO (P < 0.05 versus MCAO+INT777 + Scramble siRNA)." (PMID 32381096, 2020).
keloid (1 paper, 2022). An irregularly shaped, elevated mark on the skin caused by deposits of excessive amounts of collagen during wound healing. "BRCA1, a well-known tumor suppressor with high mutation rates in multiple cancers that was downregulated in keloid samples in this study, is highly connected to the PPI network." (PMID 36015648, 2022). "Here, we report that alterations in chromatin accessibility may underlie keloid formation, and BRCA1 suppression might contribute to the regulation of keloid formation by manipulating the accessibility of the amplifier by NPTX2." (PMID 36015648, 2022). "We conclude that BRCA1 repression inhibits the migration of DFs to the wound site, prolonging wound closure and further enhancing keloid formation." (PMID 36015648, 2022). "Breast cancer type 1 (BRCA1) was significantly downregulated in keloid DFs, and its knockdown promoted the proliferation and attenuated the migration ability of normal DF cells." (PMID 36015648, 2022). "We performed a BRCA1 CUT&Tag-seq in keloids and normal DFs to further investigate the regulatory relationship between BRCA1 and NPTX2." (PMID 36015648, 2022). "Given the previous reports on BRCA1 in chromatin remodeling, we proposed that BRCA1 suppression in keloids attenuated the accessibility of the NPTX2 enhancer and dismissed the interaction between the NPTX2 enhancer and promoter, resulting in NPTX2 repression." (PMID 36015648, 2022). "As a result, consistent with the signal landscape at NPTX2, the binding signal of BRCA1 at TP63 is lower in keloid DF than normal DF and the chromatin is denser at the corresponding region in keloid DF." (PMID 36015648, 2022). "In this study, BRCA1 expression was significantly repressed in keloid samples, implying that BRCA1 might inhibit keloid formation in the wound-healing process." (PMID 36015648, 2022). "BRCA1 binds directly to an amplification region associated with the NPTX2 promoter in normal DFs but not in keloid DFs." (PMID 36015648, 2022). "In conclusion, this study identified BRCA1 inhibition in DFs as a novel pathological factor in keloids and preliminarily explored its potential mechanisms, which will help us understand the formation of keloids." (PMID 36015648, 2022). "This implies that BRCA1 suppression could induce the perturbation of keloid-related molecular events in normal DFs, potentially representing a keloid pathogenesis factor." (PMID 36015648, 2022). "We inferred that BRCA1 suppression might induce keloids by promoting DF deposition and prolonging the wound-healing process." (PMID 36015648, 2022). "Unexpectedly, BRCA1 inhibition significantly repressed the migration ability of normal DFs, meaning that BRCA1 should promote DF migration during wound-healing, a cell event that might enhance keloid formation, according to some previous studies." (PMID 36015648, 2022).
Lacrimal Gland Tumors (1 paper, 2018). "In contrast, distribution of vimentin is abundant in tumor (upper left) than normal region (lower right) and elevated in poorly differentiated (right) than well-differentiated tumor (left), suggesting induction of vimentin according to the aggressiveness of the BRCA1-associated lacrimal gland tumor." (PMID 30652068, 2018). "However, there is no report of lacrimal gland tumor with alterations in BRCA1 in human." (PMID 30652068, 2018).
larynx cancer (1 paper, 2021). A primary or metastatic malignant neoplasm involving the larynx. "Interestingly, we identified a patient with double heterozygous PALB2 c.857delC and BRCA1 c.3286C>T mutations who was diagnosed with bilateral breast, ovarian, and larynx cancers." (PMID 34439348, 2021).
Leukopenia (1 paper, 2019). "Leukopenia was the most common severe toxicity, occurring in 7% and 8% of BRCA1 carriers and wild‐type (P = .58) and 15% and 10% of BRCA2 carriers and wild‐type (P = .24), respectively." (PMID 31407530, 2019).
leukoplakia (1 paper, 2025). A white patch or plaque on a mucous membrane that cannot be characterized clinically or pathologically as any other disease. "Studies on oral leukoplakia (OLK) further suggest that BRCA1 and BRCA2 expression levels may distinguish high-risk dysplastic lesions that progress to carcinoma from those that remain benign." (PMID 40224184, 2025).
lipoma (1 paper, 2019). A benign, usually painless, well-circumscribed lipomatous tumor composed of adipose tissue. "This is notable since of the ten tumors that were sequenced, the only tumor without a deletion of BRCA1/2 (P31) was also the only benign one (a lipoma), while the other ten tumors were malignant ovarian-, breast- and pancreatic tumors." (PMID 31029168, 2019).
low grade glioma (1 paper, 2023). A grade I or grade II glioma arising from the central nervous system. "The BRCA1 variant was initially present in the father who developed a low-grade glioma (LGG) and inherited by his son who developed an ERMS." (PMID 37377903, 2023).
lymphopenia (1 paper, 2013). Reduction in the number of lymphocytes.
metastatic colorectal cancer (1 paper, 2022). "In summary, our case presented a rare case of metastatic colorectal cancer as the primary phenotype of BRCA1 associated HBOC and benefited from PARP (poly (ADP-ribose) polymerase) inhibitor of olaparib." (PMID 36463302, 2022).
Miscarriage (1 paper, 2024). A pregnancy that ends at a stage in which the fetus is incapable of surviving on its own, defined as the spontaneous loss of a fetus before the 22th week of pregnancy. "AhR/lnc‐HZ10/BRCA1 axis can be considered as a promising target for alleviation of unexplained miscarriage." (PMID 38286681, 2024). "Based on these observations, we suggested that the AhR/lnc‐HZ10/BRCA1 axis might be considered as a promising target for treatment against unexplained miscarriage." (PMID 38286681, 2024). "Collectively, these results showed that HR repair, as indicated by lower levels of BRCA1 and RAD51 and higher levels of DSB, was suppressed in RM versus HC villous tissues and the defective HR repair in villous tissues was associated with miscarriage." (PMID 38286681, 2024). "Therefore, it is suggested that AhR/lnc‐HZ10/BRCA1 axis may be a promising target for alleviation of unexplained miscarriage." (PMID 38286681, 2024).
mucosal melanoma (1 paper, 2019). A melanoma that arises from a mucosal site. "Prior to our study, BRCA1 and BRCA2 have not been associated with mucosal melanoma and thus we extend the list of genes linked to this disease." (PMID 30664638, 2019).
oncocytoma (1 paper, 2014). "Interestingly, several cancer-related genes (VHL, HIF1A, cMET, phosphatase and tensin homolog, TSC1, BCL2, BRCA1), which include some tumor suppressors, were also found to be overexpressed in both the benign oncocytoma-like region and the high-grade oncocytic carcinoma region." (PMID 25275525, 2014).
ovarian germ cell tumor (1 paper, 2025). A neoplasm that arises from the ovary and originates from germ cells. "Although rare, ovarian germ cell tumors have been reported in carriers of BRCA1/2 mutations." (PMID 40894989, 2025).
Pancytopenia (1 paper, 2022). An abnormal reduction in numbers of all blood cell types (red blood cells, white blood cells, and platelets). "We have previously reported that, in mice, Brca1 deficiency in the hematopoietic system leads to pancytopenia and, as a result, early lethality." (PMID 36346676, 2022). "In this report and in our prior publication, we show that hematopoietic Brca1 deficiency in mice leads to pancytopenia." (PMID 36346676, 2022).
papillary breast carcinoma (1 paper, 2024). "In addition, the patient had encapsulated intracystic papillary breast carcinoma with rare foci of infiltration of surrounding stroma, and no BRCA1/2 mutation." (PMID 39217593, 2024).
papillary thyroid carcinoma (1 paper, 2025). "The results of this study show that polymorphisms of BRCA1 were significantly related to the susceptibility to papillary thyroid carcinoma in the Korean population." (PMID 40361383, 2025). "Background/Objectives: We sought to evaluate the association between the risk of papillary thyroid carcinoma (PTC) and single-nucleotide polymorphisms (SNPs) of breast cancer genes 1 (BRCA1) and 2 (BRCA2)." (PMID 40361383, 2025). "However, the association of BRCA1/BRCA2 genetic polymorphism with the risk of papillary thyroid carcinoma (PTC) has not been thoroughly investigated." (PMID 40361383, 2025).
penile cancer (1 paper, 2024). A primary or metastatic malignant neoplasm that affects the penis. "BRCA1/2 mutations are associated with impaired DNA double-strand break repair and are among the common mutations in penile cancer, potentially paving the way for poly ADP-ribose polymerase inhibitor therapy." (PMID 38336701, 2024).
penile squamous cell carcinoma (1 paper, 2025). "Despite the rarity of penile squamous cell carcinoma, BRCA1 and BRCA2 mutations were identified in both cases analyzed, suggesting homologous recombination deficiency and potential sensitivity to PARP inhibitors." (PMID 41395625, 2025).
pituitary adenoma (1 paper, 2022). "Interestingly, correlation between CN and expression was also apparent for the M6 pituitary adenoma, with RAD50 overexpression correlating with CN gain, and BRCA1 expression loss correlating with CN loss." (PMID 35978432, 2022).
primary immunodeficiencies (1 paper, 2018). "WES revealed heterogeneous genetic background among CVID patients with tumors, identifying gene variants associated with primary immunodeficiencies (such as CTLA4, PIK3CD, PMS2) and/or increased cancer susceptibility (including BRCA1, RABEP1, EP300, KDM5A)." (PMID 30723478, 2018).
proctitis (1 paper, 2020). An inflammatory process affecting the anus. "Our findings report several novel genes that have been observed to be associated with known BRCA1-ATM-RAD50 damage response complex which are activated in response to radiation, thus extending our understanding of these new players and their multifactorial roles associated with proctitis." (PMID 33008348, 2020).
retinal diseases (1 paper, 2018). "Therefore, the present study provides biochemical and histochemical evidence supporting that Brca1 could be a target for neuroprotection under damage conditions and 5-Aza-CdR a potential drug for the therapy of retinal diseases." (PMID 29673145, 2018).
Salivary gland tumors (1 paper, 2026). "Salivary gland tumors (SGTs) have been reported in BRCA1/2 carriers and suggested as part of an extended HBOC phenotype based on epidemiological associations." (PMID 41647838, 2026).
serous cystadenoma (1 paper, 2012). A serous neoplasm in which the cysts and papillae are lined by a single layer of cells without atypia, architectural complexity or invasion. "The first model exploiting the tissue-specific expression of Cre recombinase used the Fshr promoter to inactivate loxP-flanked (floxed) Brca1 alleles in granulosa cells, however serous cystadenomas carrying unrecombined Brca1 developed in the OSE." (PMID 23190474, 2012).
spina bifida (1 paper, 2023). A congenital neural tube defect in which vertebrae are not fully formed.
sterility (1 paper, 2022). "No patient who underwent general anesthesia had sterility, ectopic pregnancy or BRCA1/2 mutation as surgical indication." (PMID 35759109, 2022).
sweat gland tumors (1 paper, 2025). "We have described sweat gland tumors with HRD-associated germline PALB2, BRCA1, and PMS2 mutations." (PMID 40948682, 2025).
T-cell lymphoma (1 paper, 2014). "Our result showed that the WRN 787 TT genotype was associated with a decreased risk of only NHL, and NHL including DLBCL and T-cell lymphoma for BRCA1 871 TT genotype." (PMID 24756092, 2014). "The OGG1 326 GG and BRCA1 871 TT genotypes were associated with a decreased risk for NHL (OROGG1 GG = 0.70, p = 0.008; ORBRCA1 TT = 0.71, p = 0.048), DLBCL (OROGG1 GG = 0.68, p = 0.02; ORBRCA1 TT = 0.62, p = 0.04), and T-cell lymphoma (OROGG1 GG = 0.59, p = 0.04; ORBRCA1 TT = 0.42, p = 0.04)." (PMID 24756092, 2014).
Telangiectasia (1 paper, 2021). Telangiectasias refer to small dilated blood vessels located near the surface of the skin or mucous membranes, measuring between 0.5 and 1 millimeter in diameter. "On the other hand, as already shown, alterations in non-BRCA1/2 HRR genes may confer sensitivity not only to PARP inhibitors but also to the WEE1 checkpoint inhibitor or the ataxia telangiectasia and Rad3-related protein inhibitor." (PMID 33800556, 2021).
thoracic cancer (1 paper, 2023). A primary or metastatic malignant neoplasm affecting the tissues of the thorax. "Among those with thoracic cancers, five of 69 (7%) cases had a BRCA1/2 mutation (3 germline, 1 somatic, and 1 somatic variant of uncertain significance)." (PMID 36964191, 2023). "In the thoracic cancer cohort, OS was shorter in the 7% of patients with BRCA1/2 mutations." (PMID 36964191, 2023). "BRCA1/2 alterations are currently the main biomarkers of HRD and were frequently detected in our gastrointestinal and thoracic cancer cohort, often resulting in high SBS3 exposure and high HRD score." (PMID 36964191, 2023).
X-linked disease (1 paper, 2011). X-linked form of disease. "Similar findings were reported for the BRCA1 and BRCA2 genes and even for genes involved in X-linked diseases although allelic drop-out is expected to be less severe in X-linked diseases due to hemizygosity of the mutant allele in the affected males." (PMID 22125493, 2011).